GPR18 (G protein-coupled receptor 18)
Diseases named in the same sentence as GPR18 in open-access papers (continued):
Sharing a sentence is not in itself a finding about the gene and the disease.
depression (2 papers, 2023 to 2024). "We identified six core genes (GRB10, TDRD9, BCL7A, GPR18, KLRG1, and THEM4) significantly associated with depression and cancer." (PMID 39867577, 2024). "The results indicated that BCL7A (AUC: 0.656), GPR18 (AUC: 0.9677), GRB10 (AUC: 0.678), KLRG1 (AUC: 0.661), TDRD9 (AUC: 0.698), and THEM4 (AUC: 0.678) exhibit high diagnostic value for depression." (PMID 39867577, 2024). "This study conducted a comprehensive bioinformatics analysis, identifying six core genes (BCL7A, GPR18, GRB10, KLRG1, TDRD9, and THEM4) associated with depression and validating their diagnostic value in the context of the disorder." (PMID 39867577, 2024). "In depression, GRB10 and TDRD9, involved in cell growth and stress responses, exhibited elevated expression, while BCL7A, GPR18, KLRG1, and THEM4, linked to immune regulation and apoptosis, showed reduced expression, suggesting dysregulated cellular signaling and impaired immune function." (PMID 39867577, 2024). "The involvement of GPR18 in metabolic pathways emphasizes its role in cellular energy homeostasis and neurotransmitter biosynthesis, which are critical for brain function and may be impaired in depressive disorders." (PMID 39867577, 2024). "qPCR results demonstrated that, compared to the normal control group, the expression of GRB10 and TDRD9 was significantly elevated in the blood of depression patients, while the expression of BCL7A, GPR18, KLRG1, and THEM4 was significantly reduced." (PMID 39867577, 2024). "We identified six core genes (BCL7A, GPR18, GRB10, KLRG1, TDRD9, and THEM4), confirming their critical value in diagnosing depression." (PMID 39867577, 2024). "Among them, GRB10 and TDRD9 were significantly upregulated, while BCL7A, GPR18, KLRG1, and THEM4 were significantly downregulated in patients with depression." (PMID 39867577, 2024). "To more accurately predict and assess the progression of depression, we constructed a nomogram model for depression diagnosis based on the core genes (GRB10, TDRD9, BCL7A, GPR18, KLRG1, and THEM4) using the rms package." (PMID 39867577, 2024). "To investigate the correlation between cancer and depression, we examined the expression of BCL7A, GPR18, GRB10, KLRG1, TDRD9, and THEM4 across various cancer types using the TCGA database." (PMID 39867577, 2024). "These pathways suggest that BCL7A, GPR18, KLRG1, and THEM4 play roles in immune signaling and metabolic pathways, further underscoring their relevance to depression." (PMID 39867577, 2024). "The results showed that the expression levels of GRB10 and TDRD9 were significantly increased in depression patients compared to the control group, while the expression levels of BCL7A, GPR18, KLRG1, and THEM4 were significantly decreased, all with statistical significance." (PMID 39867577, 2024). "Similarly, BCL7A, GPR18, KLRG1, and THEM4, which are downregulated in depression, also exhibit diverse expression trends across cancers." (PMID 39867577, 2024).
epilepsy (2 papers, 2025). A brain disorder characterized by episodes of abnormally increased neuronal discharge resulting in transient episodes of sensory or motor neurological dysfunction, or psychic dysfunction. "The orphan/atypical GPCRs (GPR55, GPR119, and GPR18) carry links to epilepsy and inflammatory hyper-excitability (GPR55), incretin biology and insulin release (GPR119), and tone in blood vessels with traffic of leukocytes (GPR18)." (PMID 41303442, 2025).
Hypertension (2 papers, 2020 to 2026). The presence of chronic increased pressure in the systemic arterial system. "Our recent results showed that GPR18 deletion induced endothelial dysfunction related to NO and eNOS expression in femoral arteries altering the endothelial-dependent vasodilatation associated with hypertension in aged mice." (PMID 41596488, 2026). "Indeed, similar results were found in a murine model of hypertension, where GPR18 agonism by RvD2 could prevent hypercontractility in the thoracic aorta only, whereas no beneficial effects were observed in the small mesenteric arteries." (PMID 41596488, 2026). "Accordingly, the hypertension-induced enhancement in oxidative stress does not fit well to the changes in receptor densities since in both hypertension models, a decreased pro-oxidative receptor (CB1) was connected with an increased anti-oxidative receptor (GPR18)." (PMID 32075117, 2020). "However, we recently reported GPR18 deletion induced hypertension in older, but not in young mice." (PMID 41596488, 2026).
lung carcinoma (2 papers, 2020 to 2021). "However, the functions of GPR18 have not been yet investigated in lung cancer." (PMID 34326698, 2021).
amyotrophic lateral sclerosis (1 paper, 2025). Amyotrophic lateral sclerosis (ALS) is a neurodegenerative disease characterized by progressive muscular paralysis reflecting degeneration of motor neurons in the primary motor cortex, corticospinal tracts, brainstem and spinal cord. "Plasma resolvins were able to distinguish phenotypic variants of amyotrophic lateral sclerosis, and higher GPR32/GPR18 median expression was associated with longer survival." (PMID 39816195, 2025).
asthma (1 paper, 2024). "The authors also reported higher expression of GPR18 on peripheral blood eosinophils of patients with severe asthma." (PMID 38542895, 2024).
bacterial sepsis (1 paper, 2022). "RvD2 (0.01–10 ng/mouse) limits PMN infiltration in acute inflammation and controls bacterial sepsis via its receptor DRV2/GPR18 in mice (and review)." (PMID 35508275, 2022).
cardiac hypertrophy (1 paper, 2018). "Similar effects of DRV2/GPR18 activation were also observed in diabetic rats, where it ameliorated the diabetes-induced increase in vagal dominance and reduced oxidative stress of the myocardium, without impacting the diabetic-evoked cardiac hypertrophy and impaired control of glycaemia." (PMID 30487747, 2018).
cervical cancer (1 paper, 2022). A primary or metastatic malignant neoplasm involving the cervix. "Notably, GPR18 expression is also associated with better prognosis in cervical cancer (CESC), another HPV+ tumor, as well as in different malignancies such as urothelial bladder carcinoma (BLCA), mesothelioma (MESO) and skin cutaneous melanoma (SKCM), further corroborating its tumor-protective role." (PMID 35742918, 2022).
Chronic colitis (1 paper, 2022). A chronic inflammatory disease of the large intestine (colon, cecum and rectum). "Furthermore, the GPR18 small molecule agonist PSB-KK-1415 reduced visceral pain in a chronic colitis model induced by TNBS." (PMID 36389671, 2022).
Crohn disease (1 paper, 2022). A gastrointestinal disorder characterized by chronic inflammation involving all layers of the intestinal wall, noncaseating granulomas affecting the intestinal wall and regional lymph nodes, and transmural fibrosis. "Using publicly available microarray data of colon biopsies, we found that, like GPR183, GPR18 transcripts also were increased in the colons of UC and Crohn’s disease patients." (PMID 36389671, 2022).
dyslipidemia (1 paper, 2026). "Although RvD2 improved vascular dysfunction in AngII-treated mice, either in the absence or presence of dyslipidemia, no protective effect of GPR18 agonism through systemic RvD2 delivery was observed on the arterial stiffening of the small mesenteric arteries." (PMID 41596488, 2026).
E. coli infections (1 paper, 2015). "We next challenged Gpr18-/- or control chimeras with Citrobacter rodentium, a model of enteropathogenic E. coli infections." (PMID 26197390, 2015).
eating disorder (1 paper, 2023). A broad group of psychological disorders with abnormal eating behaviors leading to physiological effects from overeating or insufficient food intake. "Further investigations are necessary to fully elucidate the potential of GPR18 as a therapeutic target for mood, pain, and/or eating disorders." (PMID 37240392, 2023). "Thus, the orphan GPR18 may provide a novel therapeutic target for mood, pain, and/or eating disorders, and further investigation is warranted to better discern its function." (PMID 37240392, 2023).
endometriosis (1 paper, 2025). The growth of functional endometrial tissue in anatomic sites outside the uterine body. "The expression of CB1, CB2 and TRPV1 has been previously reported in the endometrium and endometriotic lesions, while this study represents the first experimental evidence as regards the expression of the receptor GPR18 in endometriosis." (PMID 41294926, 2025).
endothelial dysfunction (1 paper, 2026). In vascular diseases, endothelial dysfunction is a systemic pathological state of the endothelium (the inner lining of blood vessels) and can be broadly defined as an imbalance between vasodilating and vasoconstricting substances produced by (or acting on) the endothelium. "The current study extends the recent establishment of endothelial dysfunction in GPR18-deficient mice by showing the direct effects of GPR18 deletion on vasoconstriction, arterial stiffness, and ECM remodeling." (PMID 41596488, 2026).
glioblastoma multiforme (1 paper, 2016). "Two glioblastoma multiforme cell lines (which endogenously express GPR18) were assayed for NAGly-induced pERK phosphorylation, with negative results." (PMID 27018161, 2016).
graft versus host disease (1 paper, 2015). An immune system disorder that occurs after allogeneic hematopoietic stem cell transplant and is a reaction of donor immune cells against host tissues. "Gpr18-/- chimeras show no changes in susceptibility to intestinal insults such as Citrobacter rodentium infections or graft versus host disease." (PMID 26197390, 2015). "We next sought to test the importance of GPR18 in the context of graft versus host disease (GvHD)." (PMID 26197390, 2015).
heart failure (1 paper, 2022). Inability of the heart to pump blood at an adequate rate to meet tissue metabolic requirements. "Recently GPR18 was detected on cardiomyoblasts from patients with heart failure." (PMID 35142983, 2022). "GPR18 expression may be increased in response to injury, and its inactivation may promote heart failure chronicity." (PMID 35142983, 2022).
Hypercholesterolemia (1 paper, 2022). An increased concentration of cholesterol in the blood. "Post hoc analysis revealed that the potency of the agonists for GPR18-related relaxation was reduced in males, by smoking, and hypercholesterolemia compared to respective controls." (PMID 35163351, 2022).
ischemia (1 paper, 2023). A hypoperfusion of the BLOOD through an organ or tissue caused by a PATHOLOGIC CONSTRICTION or obstruction of its BLOOD VESSELS, or an absence of BLOOD CIRCULATION. "For instance, Gpr18-deficient mice also showed defects in reperfusion following hindlimb muscle ischemia, indicating that this receptor also plays a role in revascularization." (PMID 37645248, 2023).
mood disorder (1 paper, 2023). A cognitive disorder a disturbance in which the person's mood is hypothesized to be the main underlying feature. "The study sought to investigate the potential role of GPR18 in food intake, body temperature regulation, mood disorders, and acute and chronic (neuropathic) pain." (PMID 37240392, 2023).
Nausea (1 paper, 2021). A sensation of unease in the stomach together with an urge to vomit. "However, the GPR18 agonist is likely to affect body weight by inducing gastrointestinal disorders such as nausea." (PMID 33809564, 2021).
neuroblastoma (1 paper, 2024). Neuroblastoma (NB) is the most common solid, extracranial childhood tumor. "Six characteristic genes (BATF, CXCR3, GIMAP5, GPR18, ISG20, and IGHM) were identified by machine learning, and these genes are associated with multiple immune-related pathways and immune cells in neuroblastoma." (PMID 39559348, 2024). "BATF, CXCR3, GIMAP5, GPR18, IGHM have lower expression in high-risk neuroblastoma patients." (PMID 39559348, 2024). "BATF, CXCR3, GIMAP5, GPR18, ISG20, and IGHM may serve as biomarkers that reflect the conditions of the immune microenvironment of neuroblastoma and hold promise in guiding neuroblastoma treatment." (PMID 39559348, 2024).
pancreatic cancer (1 paper, 2020). "The role of GPR18 in tumors is not clear, and this study revealed its prognostic role in pancreatic cancer for the first time." (PMID 33169793, 2020).
pneumonia (1 paper, 2022). An acute, acute and chronic, or chronic inflammation focally or diffusely affecting the lung parenchyma, caused by an infection in one or both of the lungs (by bacteria, viruses, fungi, or mycoplasma.). "Nevertheless, several of them, SELL, GZMB, and CCR7 (at 3 dpi), and HAVCR2 (TIM-3), TNFRSF9 (CD137), and GPR18 (at 6 dpi) were promptly upregulated for the virulent Lena strain, probably associated with the marked clinical signs, the earlier and stronger peak of replication, and severe pneumonia." (PMID 34851149, 2022).
pulmonary arterial hypertension (1 paper, 2022). Pulmonary arterial hypertension (PAH) is a group of diseases characterized by mean pulmonary artery pressure >20 mmHg and elevated pulmonary arterial resistance leading to right heart failure. "GPR18, which appears to exhibit lower activity in hPAs from male, smoking or hypercholesterolemic patients, may become a new target for the treatment of pulmonary arterial hypertension." (PMID 35163351, 2022). "GPR18, the activity of which is reduced by endothelial denudation and is lower in hPAs from male, hypercholesterolemic, or smoking patients, may become a new target for the treatment of pulmonary arterial hypertension." (PMID 35163351, 2022).
cancer (13 papers, 2017 to 2024). A tumor composed of atypical neoplastic, often pleomorphic cells that invade other tissues. "Studies report that modulation of GPR18 has been associated with immunomodulation, cancer, or metabolism." (PMID 34484417, 2021). "The possible spectrum of therapeutic potential for GPR18 includes the treatment of immune, pain, neurodegenerative, and cancer processes, metabolism, and reduction in intraocular pressure." (PMID 35887268, 2022). "While its signaling pathways and biological significance have not yet been fully elucidated, increasing evidence points to the therapeutic potential of GPR18 in relation to immune, neurodegenerative, and cancer processes to name a few." (PMID 35887268, 2022). "GPR18 showed higher correlation coefficients with all three CYT, Teff, and IFNG scores than MS4A1 in the nine GPR18-prognositc cancer types, as well as 19 additional cancer types (except for DLBC)." (PMID 32398659, 2020). "In pan-cancers, GPR18 mRNA expression levels demonstrated extremely significant Pearson correlations (Pearson R values) with MS4A1 and TIL-B levels across all 29 cancer types, except for DLBC and UVM (R > 0.2, P < 0.0001)." (PMID 32398659, 2020). "Subsequent bioinformatics discovery for TIL-B prognostic gene identifies a single gene, GPR18 with stand-alone prognosticity across 9 cancers (superior over CD20), with further validations in multiple non-TCGA cohorts." (PMID 32398659, 2020). "GPR18 expressions in tumors are strongly correlated with major T-cell functionality scores, suggesting its functional link to cytolytic T-cell activity in cancer." (PMID 32398659, 2020). "Strikingly, GPR18 was found to be almost uniformly clustered with B-cell gene sets involved in B-cell–T-cell interactions in 7/9 cancers." (PMID 32398659, 2020). "Strikingly, further filtering with Cox-regression P value < 0.05 exposed a single gene named GPR18, whose mRNA expression levels displayed significant prognosticity across nine cancer types (log-rank test P < 0.05, median TPM cutoff)." (PMID 32398659, 2020). "Here, we first identified a previously unreported B-cell prognostic gene, GPR18, whose expressions have versatile prognosticity in as many as nine cancer types, which is superior over CD20 protein and MS4A1 mRNA." (PMID 32398659, 2020). "Potential therapeutic applications for GPR18 include intraocular pressure, metabolic disorders, and cancer." (PMID 31075933, 2019). "The varied impact of GPR18 highlights the complexity of immune modulation in cancer, suggesting its role may differ across tumor types." (PMID 39867577, 2024). "As this review focuses on the receptors of the endocannabinoid system that are implicated in cancer cell invasion, the focus will be placed on CB1, CB2, as well as GPR55 and GPR18, receptors that have been the focus of research examining the effects of cannabinoids on cancer cell invasion." (PMID 34313032, 2022). "Furthermore, we first uncovered GPR18’s potential link to cytolytic T-cell activity across pan-cancers." (PMID 32398659, 2020). "Instead, MS4A1, TIL-B, or potentially GPR18 may represent more versatile B-cell markers for prognosis in human cancers." (PMID 32398659, 2020). "As a single gene, detection of GPR18 mRNA could be more versatile than MS4A1 mRNA for pan-cancer prognosis (predictive in nine vs. six cancer types, respectively)." (PMID 32398659, 2020). "Thus, adopting GPR18 for infiltrating B-cell assessment and cancer prognosis can be feasible in theory." (PMID 32398659, 2020). "GPR18's immune signature denotes major B-cell-T-cell interactions, with its intratumoral expression strongly tied to a “T-cell active”, likely cytolytic, status across human cancers, suggesting its functional link to cytolytic T-cell activity in cancer." (PMID 32398659, 2020). "In conclusion, quantitative levels of GPR18, MS4A1, and TIL-B are reliable biomarkers for intratumoral B-cell assessments over CD20 protein, especially for prognostic purposes in cancer." (PMID 32398659, 2020).